SLC20A1 (solute carrier family 20 member 1)
Description:
Sodium-phosphate symporter which preferentially transports the monovalent form of phosphate with a stoichiometry of two sodium ions per phosphate ion. May play a role in extracellular matrix and cartilage calcification as well as in vascular calcification. Essential for cell proliferation but this function is independent of its phosphate transporter activity. (Microbial infection) May function as a retroviral receptor as it confers human cells susceptibility to infection to Gibbon Ape Leukemia Virus (GaLV), Simian sarcoma-associated virus (SSAV) and Feline leukemia virus subgroup B (FeLV-B) as well as 10A1 murine leukemia virus (10A1 MLV).
Synonyms: GLVR-1; PiT-1; GLVR1; PIT1
Tractability: Antibody: UniProt places it where antibodies can reach, with high confidence; its Gene Ontology location is reachable by antibodies, with high confidence; UniProt predicts a signal peptide or a membrane-spanning region; the Human Protein Atlas places it where antibodies can reach. PROTAC: ubiquitination databases record sites on it; its protein half-life has been measured; a small molecule that binds it is known.
Target class: Electrochemical transporter; SLC20 family of sodium-dependent phosphate transporters; Transporter; SLC superfamily of solute carriers
Gene: Protein-coding gene on chromosome 2 (112,645,854 to 112,663,829, forward strand). Ensembl gene ENSG00000144136.
Subcellular location: Cell membrane
Subcellular location (Human Protein Atlas): Plasma membrane
Pathways (Reactome):
Transport of small molecules: Sodium-coupled phosphate cotransporters
Gene Ontology:
Molecular function: sodium:phosphate symporter activity; signaling receptor activity; high-affinity phosphate:sodium symporter activity; phosphate transmembrane transporter activity
Biological process: cell population proliferation; positive regulation of canonical NF-kappaB signal transduction; phosphate ion transmembrane transport; phosphate-containing compound metabolic process; phosphate ion transport; sodium ion transmembrane transport; sodium ion transport
Cellular component: plasma membrane; membrane
Genetic constraint (gnomAD): Loss-of-function variants: 27 observed, 58.77 expected, observed/expected ratio (o/e) 0.46, 90% interval 0.34 to 0.63. The upper end of that interval is the gene's LOEUF score, 0.63, which puts it in group 2 of 6, group 1 being the genes least tolerant of losing a copy. Missense variants: 600 observed, 800.6 expected, observed/expected ratio (o/e) 0.75, 90% interval 0.7 to 0.8. Synonymous variants: 270 observed, 284.14 expected, observed/expected ratio (o/e) 0.95, 90% interval 0.86 to 1.05.
Homologues: Orthologues: chimpanzee SLC20A1 (99% identical), macaque SLC20A1 (97% identical), dog SLC20A1 (96% identical), pig SLC20A1 (95% identical), rabbit SLC20A1 (94% identical), mouse Slc20a1 (91% identical), rat Slc20a1 (91% identical), guinea pig SLC20A1 (91% identical), tropical clawed frog slc20a1 (77% identical), zebrafish slc20a1b (68% identical), zebrafish slc20a1a (61% identical), Drosophila melanogaster NaPi-III (40% identical), and 5 more. Paralogues in human: SLC20A2 (59% identical).